ACKR4 (atypical chemokine receptor 4)
Description:
Atypical chemokine receptor that controls chemokine levels and localization via high-affinity chemokine binding that is uncoupled from classic ligand-driven signal transduction cascades, resulting instead in chemokine sequestration, degradation, or transcytosis. Also known as interceptor (internalizing receptor) or chemokine-scavenging receptor or chemokine decoy receptor. Acts as a receptor for chemokines CCL2, CCL8, CCL13, CCL19, CCL21 and CCL25. Chemokine-binding does not activate G protein-mediated signal transduction but instead induces beta-arrestin recruitment, leading to ligand internalization. Plays an important role in controlling the migration of immune and cancer cells that express chemokine receptors CCR7 and CCR9, by reducing the availability of CCL19, CCL21, and CCL25 through internalization. Negatively regulates CXCR3-induced chemotaxis. Regulates T-cell development in the thymus.
Synonyms: CC-CKR-11; CCR-11; CCRL1; CCBP2; CCR11; VSHK1; CCX-CKR; PPR1; CCR10; CCX CKR; CKR-11
Tractability: Small molecule: it belongs to a druggable protein family. Antibody: UniProt places it where antibodies can reach, with high confidence; its Gene Ontology location is reachable by antibodies, with high confidence; UniProt predicts a signal peptide or a membrane-spanning region.
Gene: Protein-coding gene on chromosome 3 (132,597,270 to 132,618,967, forward strand). Ensembl gene ENSG00000129048.
Subcellular location: Early endosome; Recycling endosome; Cell membrane
Subcellular location (Human Protein Atlas): Mitochondria; Vesicles
Pathways (Reactome):
Signal Transduction: Chemokine receptors bind chemokines
Gene Ontology:
Molecular function: chemokine receptor activity; protein binding; C-C chemokine binding; C-C chemokine receptor activity; chemokine binding; G protein-coupled receptor activity; scavenger receptor activity
Biological process: calcium-mediated signaling; cell chemotaxis; chemotaxis; G protein-coupled receptor signaling pathway; immune response; positive regulation of cytosolic calcium ion concentration; chemokine-mediated signaling pathway; vesicle-mediated transport
Cellular component: external side of plasma membrane; plasma membrane; early endosome; membrane; recycling endosome
Genetic constraint (gnomAD): Loss-of-function variants: 4 observed, 7.5 expected, observed/expected ratio (o/e) 0.53, 90% interval 0.26 to 1.22. That is too few expected variants to judge how well the gene tolerates losing a copy. Missense variants: 167 observed, 349.06 expected, observed/expected ratio (o/e) 0.48, 90% interval 0.42 to 0.54. Synonymous variants: 67 observed, 116.73 expected, observed/expected ratio (o/e) 0.57, 90% interval 0.47 to 0.7.
Homologues: Orthologues: chimpanzee ACKR4 (99% identical), macaque ACKR4 (96% identical), pig ACKR4 (88% identical), dog ACKR4 (86% identical), rabbit ACKR4 (86% identical), mouse Ackr4 (85% identical), rat Ackr4 (84% identical), guinea pig ACKR4 (84% identical), tropical clawed frog ackr4 (59% identical), zebrafish ackr4a (47% identical), zebrafish ackr4b (45% identical). Paralogues in human: CCR7 (37% identical), CCR9 (35% identical), CCR6 (33% identical), CCR10 (33% identical), CXCR2 (32% identical), CXCR6 (32% identical), CX3CR1 (31% identical), CCR4 (31% identical), ACKR2 (31% identical), CCR1 (30% identical), CCR5 (30% identical), CXCR4 (30% identical), and 11 more.
Diseases named in the same sentence as ACKR4 in open-access papers:
ACKR4 is named in the same sentence as 36 diseases in open-access papers, as found by Europe PMC text mining. Sharing a sentence is not in itself a finding about the gene and the disease. The quoted sentences say what the papers report.
breast cancer (5 papers, 2020 to 2022). A primary or metastatic malignant neoplasm involving the breast. "Our data are distinctive from the previous study showing that ACKR4 knockout mice delayed E0771 mammary tumor growth." (PMID 34638505, 2021). "In breast cancer, nasopharyngeal cancer, liver cancer, and cervical cancer, ACKR4 negatively regulates tumor growth and metastasis, implying a protective role in tumorigenesis." (PMID 34638505, 2021). "Expression of ACKR4 in mouse mammary cancer cells 4T1.2 resulted in increased spontaneous lung metastasis and enhanced hematogenous metastasis in vivo." (PMID 32456359, 2020). "ACKR4/CCRL1 down regulation correlates with worse outcome in breast cancer." (PMID 35754051, 2022). "Supporting these findings are the results of a breast cancer report, demonstrating that ACKR4 overexpression by breast tumor cells inhibited tumor growth and lung metastases, and decreased the expression of mouse CCL19, CCL21, CCL25 and CXCL13 chemokines in xenografts." (PMID 32582148, 2020). "Downregulated ACKR4 protein expression in the tumor as compared to normal tissue has been reported in cervical and liver cancer as well as in nasopharyngeal carcinoma, but not in gastric or breast cancers." (PMID 33374792, 2020).
nasopharyngeal carcinoma (3 papers, 2020 to 2024). A carcinoma arising from the nasopharyngeal epithelium. "Importantly, ACKR4 was previously found to inhibit the growth and metastasis of breast, cervical, colorectal, hepatocellular, and nasopharyngeal cancer cells, although no report mentioned any sex-specific bias for cancers occurring in both sexes." (PMID 39298333, 2024).
colon cancer (2 papers, 2020 to 2024). "Although ACKR4 is expressed by cancer cells of various malignancies, including breast, liver, and colon cancer, it seems that this receptor plays a protective role against tumor development." (PMID 32456359, 2020). "This is in the agreement with the protective effect of ACKR4 in human breast and colon cancer samples, in which ACKR4 downregulation was correlated with worse outcome." (PMID 32456359, 2020).
colorectal cancer (2 papers, 2021 to 2024). A primary or metastatic malignant neoplasm that affects the colon or rectum. "Loss of ACKR4 in mouse colorectal cancer cells impairs the DC migration to the tumor-draining lymph nodes, which leads to the reduced number of tumor-specific T-cells and resistance to immune checkpoint blockades." (PMID 39290345, 2024). "ACKR4 expression is reduced in human colorectal cancer (CRC) compared with normal colon epithelial cells." (PMID 39290345, 2024). "Our study demonstrated that Atypical Chemokine Receptor 4 (ACKR4) was downregulated in human colorectal cancer (CRC) compared with normal colon tissues." (PMID 34638505, 2021).
adenoma (1 paper, 2020). A neoplasm arising from the epithelium. "In neoplastic tissue, ACKR4 expression decreased gradually with a minimum of expression at score 3, that is, in patients with adenomas of the highest potential for malignancy." (PMID 33374792, 2020). "Considering the dependence of ACKR4 expression on histological type, we repeated pairwise analysis separately for patients with adenomas of tubular, tubule-villous, and villous growth patterns." (PMID 33374792, 2020). "Although non-significantly associated with a cumulative potential for malignancy, the expression of ACKR4 in adenomas was significantly dependent on its growth pattern." (PMID 33374792, 2020). "In adenomas, ACKR4 downregulation in neoplastic tissue increased with increasing potential for malignancy and contribution of villous growth pattern." (PMID 33374792, 2020). "Likewise, adenomas with tubular and tubulovillous growth patterns overexpressed ACKR4 and receptor downregulation in adenomas as compared to patient-matched normal tissue was observed solely in patients with dominant villous growth patterns." (PMID 33374792, 2020). "This resulted from a concomitant change in expression pattern in normal tissue and adenomas with significantly lower ACKR4 expression in normal tissue from patients with tubular adenomas and significantly lower ACKR4 expression in adenomas from patients with the villous type." (PMID 33374792, 2020). "ACKR4 expression ratio (normal-to-pathological) increased significantly up-to score three and subsequently decreased insignificantly along with increasing malignancy, also indicating maximal receptor downregulation in adenomas with the highest potential for malignancy." (PMID 33374792, 2020). "While patients with tubular adenomas had significantly lower ACKR4 expression than those with tubulovillous and villous adenomas regarding normal tissue, the lowest receptor expression in neoplastic tissue was observed in adenomas with prevalent villous growth pattern." (PMID 33374792, 2020).
B-cell lymphomas (1 paper, 2024). "Human datasets showed that having higher levels of ACKR4 could be linked to a better disease prognosis in male patients with Burkitt lymphoma, a rare but aggressive form of B-cell lymphoma." (PMID 39298333, 2024). "This led us to investigate the potential relevance of ACKR4 expression in human B-cell lymphomas." (PMID 39298333, 2024). "Furthermore, several lines of evidence suggest that Ackr4 might act as a tumor suppressor of Myc-driven B-cell lymphomas." (PMID 39298333, 2024). "Altogether, these analyses led us to conclude that, as in Eμ-Myc mice, ACKR4 is a male-specific positive prognostic factor in Burkitt lymphoma, the archetype of MYC-driven B-cell lymphomas." (PMID 39298333, 2024).
Burkitt lymphoma (1 paper, 2024). A rare form of malignant mature B-cell non-Hodgkin lymphoma. "This suggests that measuring ACKR4 gene expression in male patients with Burkitt lymphoma could be useful to identify the patients at higher risk, for whom specific therapeutic regimens might be required." (PMID 39298333, 2024). "Consistent with this, we found that the KO of ACKR4 in Raji Burkitt lymphoma cells led to a dramatic increase in CCL21-guided cell migration." (PMID 39298333, 2024). "ACKR4 gene expression was plotted for all patients with a Burkitt lymphoma diagnosed at age 0–17 (48 males, 29 females), classified according to sex (D, left)." (PMID 39298333, 2024). "Furthermore, the knockout of ACKR4 increased the chemokine-guided migration of Burkitt lymphoma cells." (PMID 39298333, 2024). "(F) The knockout of ACKR4 in Burkitt lymphoma Raji cells increases their CCL21-guided migration." (PMID 39298333, 2024). "ACKR4 is a male-specific prognostic factor in Burkitt lymphoma." (PMID 39298333, 2024). "However, there was again an increased survival for Burkitt lymphoma male patients with high ACKR4 expression, but not for women." (PMID 39298333, 2024).
colorectal adenoma (1 paper, 2020). An adenoma that arises from the colon or rectum. "We aimed at transcriptional analysis (RTqPCR) of ACKR2 and ACKR4 expression in colorectal adenoma-adenocarcinoma sequence in paired normal-neoplastic tissues from 96 polyps and 51 cancers." (PMID 33374792, 2020).
colorectal tumor (1 paper, 2022). "The deletion of atypical chemokine receptor 4 (ACKR4) in colorectal tumor cells but not stromal cells inhibited the migration of DCs to tumor-draining lymph nodes and impaired antigen presentation." (PMID 36189283, 2022).
dysplasia (1 paper, 2020). A usually neoplastic transformation of the cell, associated with altered architectural tissue patterns. "Neither ACKR2 nor ACKR4 expression ratios (normal-to-polyp) differed significantly depending on dysplasia grade." (PMID 33374792, 2020).
glioblastoma (1 paper, 2024). The most malignant astrocytic tumor (WHO grade IV). "We provide important details to indicate that glioblastoma cell-secreted CCL21 plays a dual role both in recruiting plasmacytoid dendritic cells via binding to CCR7 and activating plasmacytoid dendritic cells through the CCR7/ACKR4—β-arrestin/CIITA pathway." (PMID 39456552, 2024).
hepatocellular carcinoma (1 paper, 2020). A malignant tumor that arises from hepatocytes. "Both mRNA and protein expressions of ACKR4 correlated with the malignant phenotype of hepatocellular carcinoma (HCC) cells and were significantly reduced in tumor tissue compared with paired normal liver tissue." (PMID 32456359, 2020).
infarction (1 paper, 2023). A localised pathological necrosis of tissue resulting from obstruction of the blood supply usually by a thrombus, an embolus, or vascular torsion. "The expression of ACKR4 was upregulated in the border/infarct area after myocardial infarction, and knocking out ACKR4 protected against adverse ventricular remodeling in mice post-infarction, indicating that ACKR4 may be a novel therapeutic target to ameliorate cardiac remodeling." (PMID 36952494, 2023).
lymph node metastasis (1 paper, 2020). "On average, ACKR4 was significantly downregulated solely in adenocarcinomas (by 1.5-fold), less so in patients with lymph node metastasis, owing to a gradual decrease in ACKR4 expression among N0-N1-N2 cancers in non-affected tissue without changes in tumors." (PMID 33374792, 2020). "However, IHC findings on the association of ACKR4 protein expression with pathological findings have shown decreasing receptor immunopositivity along with increasing CRC stage and its lower expression in patients with lymph node metastasis." (PMID 33374792, 2020). "The ACKR4 was downregulated in tumors solely in patients without lymph node metastasis (by 2.2-fold), and its expression rates were inversely related to an increasing N stage." (PMID 33374792, 2020). "Unlike IHC studies on ACKR4 protein, which are conducted solely on pathological tissue, paired analysis of gene expression showed the ACKR4 downregulation to be less marked in more dedifferentiated tumors and in patients with lymph node metastasis." (PMID 33374792, 2020).
lymphoma (1 paper, 2024). A malignant (clonal) proliferation of B- lymphocytes or T- lymphocytes which involves the lymph nodes, bone marrow and/or extranodal sites. "Our analyses reveal that in both mice and humans Ackr4/ACKR4 is a male-specific prognostic factor in Burkitt-like lymphomas." (PMID 39298333, 2024). "ACKR4 gene expression was plotted for all lymphoma patients with clinical follow-up (91 men [M], 68 women [W]), classified according to sex (B, left)." (PMID 39298333, 2024). "In addition, Ccr7 is required for lymphoma cell lodging to secondary lymphoid organs and ACKR4 expression was inversely correlated with the metastasis capacity of different types of cancer cells." (PMID 39298333, 2024).
melanoma (1 paper, 2023). A malignant, usually aggressive tumor composed of atypical, neoplastic melanocytes. "Then, we identified 9 LR pairs (“BMP6- > HJV” 、"CCL8- > ACKR4” 、"DLL3- > NOTCH3"、"DSC3- > DSG3"、"GHRH- > GHRHR” 、"LRRC4B- > PTPRF"、"SEMA4D- > PLXNB1"、"SFRP1- > FZD6"、"UCN- > CRHR1′′) as key LR pairs in melanoma prognosis through Lasso Cox regression and Multiple Stepwise Regression." (PMID 36777724, 2023).
multiple myeloma (1 paper, 2024). "Finally, we analyzed dataset #GSE136337, comprising data from the malignant plasma cells of patients with multiple myeloma (260 men, 166 women), and found that ACKR4 is not a prognostic factor for this cancer type." (PMID 39298333, 2024).
progeria (1 paper, 2022). "ACKR4 is also among the CCL2-related DEGs that progeria and aging have in common." (PMID 36289702, 2022). "ACKR4 is the only potential CCL2 receptor that is also a DEG in aging and progeria." (PMID 36289702, 2022). "The sixth DEG, ACKR4, is downregulated in children suffering from progeria compared to healthy children and nonagenarians." (PMID 36289702, 2022). "ACKR4 has been mentioned as a receptor for CCL2 which is upregulated in nonagenarians compared to healthy children in our study, whereas the ACKR4 expression in progeria is very low in all comparisons." (PMID 36289702, 2022). "As ACKR4 was regulated in different directions in progeria and aging (downregulated in HGPS, upregulated in aging), ACKR4 might play an important role in both processes and might be involved in the severity of the symptoms or the differences between accelerated and normal aging." (PMID 36289702, 2022). "Some genes that are downregulated during aging are upregulated in progeria patients (KRT8, KRT18, UCP2, ADAMTS15, ACTN4P1) while others (ACKR4) are upregulated in nonagenarians but downregulated in children suffering from HGPS." (PMID 36289702, 2022).
Stroke (1 paper, 2023). Sudden impairment of blood flow to a part of the brain due to occlusion or rupture of an artery to the brain. "Co-expressed hub genes of EIF4E3, ZNF595, ZNF700, MATR3, ACKR4, ANXA3, SEPSECS-AS1, and RNF166 were significantly associated with AF-related stroke." (PMID 36952494, 2023). "Hub genes EIF4E3, ZNF595, ZNF700, MATR3, ACKR4, ANXA3, SEPSECS-AS1, and RNF166 have potential as novel biomarkers and therapeutic targets in AF-related stroke." (PMID 36952494, 2023). "Based on the results of DEG3 and ROC curves in GSE66724 and GSE58294, we filtered eight hub genes of AF-related stroke (AUC > 0.8), including EIF4E3, ZNF595, ZNF700, MATR3, ACKR4, ANXA3, SEPSECS-AS1, and RNF166." (PMID 36952494, 2023). "The hub genes of EIF4E3, ZNF595, ZNF700, MATR3, ACKR4, ANXA3, SEPSECS-AS1, and RNF166 may link AF and secondary stroke." (PMID 36952494, 2023). "The expression of MATR4, ACKR4, RNF166, and miR-198 in AF-related stroke patients was lower than those in AF patients without stroke." (PMID 36952494, 2023).
systemic sclerosis (1 paper, 2023). A chronic disorder, possibly autoimmune, marked by excessive production of collagen which results in hardening and thickening of body tissues. "Dysregulated CCL21 and CCL19, ligands of ACKR4, were also revealed in human PAH and CCL21 appears to be a potential biomarker for predicting the risk of PAH in systemic sclerosis." (PMID 37449198, 2023).